GRIN2A (glutamate ionotropic receptor NMDA type subunit 2A)
Diseases named in the same sentence as GRIN2A in open-access papers (continued):
Sharing a sentence is not in itself a finding about the gene and the disease.
schizophrenia (continued). "Further, knockout mouse models of GRIN2A show similarities to schizophrenia models." (PMID 37107537, 2023). "Herzog and colleagues used EEG to show that Grin2a+/− mice exhibit attenuated auditory steady-state responses at gamma frequencies, and increased gamma power during sleep, both features that have been observed in schizophrenia." (PMID 37736757, 2023). "Exome sequencing studies have uncovered rare, loss-of-function variants that greatly increase risk of schizophrenia, including loss-of-function mutations in GRIN2A (aka GluN2A or NR2A, encoding the NMDA receptor subunit 2A) and AKAP11 (A-Kinase Anchoring Protein 11)." (PMID 36914641, 2023). "These and our findings further substantiate a link between schizophrenia and epilepsy, which is affected by GRIN2A, but not AKAP11 mutation." (PMID 36914641, 2023). "Besides their genetic validity, do Grin2a and Akap11 mutant mice have any neurobiological phenotype that resembles the human disease (schizophrenia and/or bipolar disorder)?" (PMID 36914641, 2023). "Also, a large-scale exome sequencing study identified single genes whose rare mutations substantially increase the risk for schizophrenia, of which six genes (SETD1A, CUL1, XPO7, GRIA3, GRIN2A, and RB1CC1) showed odds ratios larger than ten." (PMID 36878965, 2023). "On a behavioral level, the schizophrenia-related GRIN2A variant was associated with language-related negative symptomatology." (PMID 36797233, 2023). "This convergence might imply a similar common pathway arising from the various forms of GRIN2A genetic involvement in schizophrenia." (PMID 37736757, 2023). "Indeed, GRIN2A and SP4, 2 genes implicated in schizophrenia susceptibility through both fine-mapping of GWAS loci and exome sequencing, have direct roles in NMDA receptor function and associative memory." (PMID 34974922, 2022). "Short tandem repeats and VNTRs in the cannabinoid receptor 1 (CNR1), glutamate ionotropic receptor NMDA type subunit 2A (GRIN2A), prodynorphin (PDYN), and proenkephalin (PENK) genes were reported to be associated with the vulnerability to schizophrenia and substance dependence." (PMID 35360861, 2022). "Studies in rat models have shown that GRIN2A and GRIN2B expression is upregulated in the prefrontal cortex during childhood and adolescence, while a model of schizophrenia is characterized by an immature neurobiological phenotype with reduced GRIN2A and GRIN2B expression." (PMID 34685369, 2021). "GRIN1, GRIN2A, GRIN2B, GRIN2C, and GRIN2D all encode subunits of the N-methyl-D-aspartate receptor (NMDAR), which has been shown to be involved in the development of schizophrenia." (PMID 34946799, 2021). "It is quite conceivable that GRIN2A and GRIN2B, via this DDCS, modulate the activity of the ascending monoaminergic pathways and thus cause the ‘positive’ component of schizophrenia, while changes in the prefrontal cortex and hippocampus cause negative and cognitive components to arise." (PMID 34685369, 2021). "In addition, the GRIN2A and GRIN2B genes, encoding the GluN2A (NR2A) and GluN2B (NR2B) subunit of the NMDAR respectively, are identified schizophrenia risk genes." (PMID 31824347, 2019). "Experiments in mice provide further support for a link between schizophrenia and hypofunction of GluN2A and GluN2B: Global ablation of Grin2A causes spatial working/short-term memory deficits (without impairing basic spatial processing)." (PMID 31824347, 2019). "Indeed, GRIN2A, the gene encoding the NMDAR subunit GluN2A, is also located at one of the 108 schizophrenia-associated loci (Schizophrenia Working Group of the Psychiatric Genomics Consortium, 2014)." (PMID 29867393, 2018). "Finally, a SNP within the NMDAR GRIN2A subunit gene is now genome-wide significant for schizophrenia, as are SNPs at the loci for GRIA1, GRM3 and SRR, all of which impact on NMDAR signalling." (PMID 25315827, 2015).
schizophrenia (continued). "Mice lacking the equivalent of the GRIN2A gene cause abnormal mouse behaviors similar to those observed in animal model schizophrenia." (PMID 23189055, 2012). "Also, our PPI network analysis identified NRXN, CACNA1C, and GRIN2A as hub genes in schizophrenia." (PMID 40259965, 2025). "Recent evidence from a Schizophrenia Exome Meta-Analysis (SCHEMA) consortium study also implicates protein-damaging mutations affecting synaptic genes, including the NMDA receptor subunit GRIN2A, the AMPA receptor subunit GRIA3 and a synaptic voltage-gated calcium channel (CACNA1G)." (PMID 38256020, 2024). "The reduction in GRIN1 and GRIN2A in mice bearing DYS and D3 single heterozygosis is consistent with the glutamate hypothesis for schizophrenia which specifies a role for NMDA receptors in either causing glutamatergic dysfunction or mediating cognitive and behavioral sequelae." (PMID 37240042, 2023). "The association of this clinical endophenotype with the single-nucleotide variants selected for study in the NMDA GRIN1, GRIN2A, and GRIN2B receptor coding subunits, would suggest that these SNVs could be potential markers of clozapine resistance in patients with schizophrenia." (PMID 33025395, 2021). "The aim of the study was to explore whether selected nucleotide variants in GRIN1, GRIN2A, and GRIN2B encoding subunits of the N-methyl-d-aspartate receptor (NMDA-R) receptor occur in a selected group of patients with treatment resistant schizophrenia with cognitive impairment." (PMID 33025395, 2021). "We prioritized 101 schizophrenia genes, including 15 that are targeted by approved or investigational drugs (e.g., DRD2, GRIN2A, CACNA1C, GABBR2)." (PMID 41639063, 2026). "As such, the features of the clinical presentation may not be typical of all GRIN2A-linked cases of schizophrenia and larger cohort studies are needed to validate the observations from this single case and more rigorously delineate the clinical presentation associated with dysfunction in this gene." (PMID 40701976, 2025). "This plasticity was significantly impaired in Grin2a (NR2A) knockout mice, a model of schizophrenia, which mirrors visual plasticity deficits observed in human patients." (PMID 40093861, 2025). "CACNAC1, GRIN2A, and GRM3 have already been targeted in clinical repurposing trials for schizophrenia, but these clinical trials also showed heterogeneous outcomes." (PMID 37158213, 2023). "A major finding of our study is that Grin2a and Akap11 mutants show elevated gamma power during sleep and quiet wake, consistent with EEG findings in schizophrenia and to a lesser extent, bipolar disorder patients." (PMID 36914641, 2023). "This study indicates the likely contribution of the GRIN2A, GRIN2B, GRM8, SLC1A2, and SLC17A7 genes to the development of clinical heterogeneity in schizophrenia." (PMID 36980845, 2023). "In some analyses, GRIN1, GRIN2A and GRIN2B were unchanged, but GRIN2A vs. GRIN2B ratio decreased in the PFC of patients with schizophrenia." (PMID 36833173, 2023). "Of note, variants among the GRIN3A are considered to be more relevant to autism spectrum disorders or schizophrenia, while GRIN1, GRIN2A, GRIN2B, and GRIN2D are more epilepsy-related." (PMID 38075685, 2023). "Enhancers from schizophrenia GWAS regions were found to interact with the promoters of a number of genes (DRD2, GRIN2A, CACNA1C, and FOXP1), which have previously been unambiguously linked to schizophrenia." (PMID 31963710, 2020). "These included schizophrenia candidate genes (GRIA1, RIMS1, DLGAP2, GRIN2A, and NRXN1) and several interaction partners." (PMID 25484875, 2014).
schizophrenia (continued). "GRIN2Anull-related phenotypes appear to occasionally even manifest as isolated mental disorder, i.e. as schizophrenia or mood disorder without further GRIN2A-specific symptoms, such as intellectual disability and/or epilepsy." (PMID 41087560, 2026). "Preclinical studies have indicated that GRIN2A mutations lead to NMDAR loss of function and substantially increase the risk of schizophrenia; however, their role in schizophrenia is not well understood." (PMID 39501956, 2025). "The N1/MMN peak in the difference waveform is reported to be reduced on average in schizophrenia and bipolar disorder patients; however, we found no significant changes in Grin2a or Akap11 mutant mice, perhaps because of high variability in this metric." (PMID 36914641, 2023). "In the present study, we were able to detect the contribution of the GRIN2A, GRIN2B, GRM8, SLC1A2, and SLC17A7 genes of the glutamatergic system to determining the clinical heterogeneity of schizophrenia, which is important for the prognosis and outcome of the disease." (PMID 36980845, 2023). "We found that Grin2a and Akap11 mutant mice possess several EEG features shared with human schizophrenia and bipolar disorder patients, including elevated gamma oscillations at rest, attenuated auditory steady-state responses (ASSR) at gamma frequencies, and changes in sleep spindle density." (PMID 36914641, 2023). "We did not reveal any associations of GRIN2A and GRIN2B polymorphisms with leading (positive vs. negative) symptoms or type of course (continuous vs. episodic) of schizophrenia." (PMID 34685369, 2021). "In this study, we did not identify associations of the GRIN2A and GRIN2B genes with leading symptoms or course types of schizophrenia." (PMID 34685369, 2021). "The genotypes and alleles frequency analysis of GRIN2A and GRIN2B polymorphisms detected no “modifier loci” regarding positive or negative leading symptoms of schizophrenia." (PMID 34685369, 2021). "In contrast to GRIN1, no SNVs in GRIN2A gene have been reported, in OMIM, in associations with schizophrenia and particularly with a clinical phenotype of cognitive deficit in schizophrenia." (PMID 33237434, 2021). "The significance of genetic variation of GRIN2A and GRIN2B fits well with the glutamate hypothesis for the pathophysiology of schizophrenia." (PMID 34685369, 2021). "The molecules that mostly contributed to discriminate schizophrenia from control were: VGluT2, EAAT2, GAD67, d-Asp/total Asp, d-Ser, PSD-95, GRIA1 and GRM5 whereas the ones that barely contributed to the discrimination were: l-Gln/l-Glu ratio, d-Ser/total Ser, EAAT1, GRIN2A and Gly." (PMID 35217646, 2022). "Our conclusion is that selected single-nucleotide variants in GRIN1, GRIN2A, and GRIN2B genes of NMDA-R do not seem to be associated with both resistance to schizophrenia treatment with clozapine, and also with the occurrence of cognitive disturbances in schizophrenia." (PMID 33025395, 2021). "In this study, we examined the contribution of GRIN2A and GRIN2B polymorphisms to the clinical features of schizophrenia, specifically the leading symptoms (negative or positive), course type (continuous or episodic), as well as the age of onset of the disease." (PMID 34685369, 2021). "Moreover, exome-sequencing studies revealed that rare damaging mutations in GRIN1, GRIN2A, and GRIN2B, which are expected to cause NMDAR hypofunction directly, are found in samples from schizophrenia patients, but not controls." (PMID 31824347, 2019). "The study aimed to examine whether four selected single nucleotide variants in GRIN1, GRIN2A and GRIN2B encoding NMDA-R subunits, of which two have not been tested before, are linked with the selected clinical phenotype of cognitive dysfunction in schizophrenia." (PMID 33237434, 2021).
epilepsy (130 papers, 2014 to 2026). A brain disorder characterized by episodes of abnormally increased neuronal discharge resulting in transient episodes of sensory or motor neurological dysfunction, or psychic dysfunction. "Given the familial nature of their epilepsy, genetic testing revealed a heterozygous pathogenic variant in the GRIN2A gene, c.1553G > A p.(Arg518His)." (PMID 40727434, 2025). "An important additional genetic finding in this case is a pathogenic splice donor mutation in GRIN2A, a well-established epilepsy and ASD candidate gene, especially regressive ASD." (PMID 40894167, 2025). "Our findings demonstrate that SCZ-associated GRIN2A variants were predominantly loss-of-function (LoF), whereas epilepsy and DD/ID-associated variants resulted in both gain- and loss-of-function phenotypes." (PMID 38307912, 2024). "This study has identified two genetic variants of the GRIN2A gene in patients with epilepsy‐aphasia syndrome." (PMID 39474911, 2024). "An illustration of this can be the identification of variants in GRIN2A, the gene that encodes GluN2A subunits in NMDARs, being the predominant monogenic cause of epilepsy‐aphasia spectrum (EAS) syndrome." (PMID 39474911, 2024). "Mutations in GRIN2A can disrupt these processes, often affecting the pediatric population and causing various neurological disorders characterized by epilepsy, intellectual disability, and aphasia, among other neuropsychiatric findings." (PMID 39050322, 2024). "Although GRIN2A mutations can present with epilepsy, aphasia, and various neuropsychiatric manifestations, they have not previously been associated with LE." (PMID 39050322, 2024). "Our data demonstrate that GRIN2A missense variants associated with either epilepsy, DD/ID or SCZ can result in LoF of the NMDAR." (PMID 38307912, 2024). "The next most promising candidate gene for CAS was GRIN2A, which is also associated with the epilepsy-aphasia syndromes, now termed developmental and/or epileptic encephalopathy with spike-wave activation in sleep, and including Llandau-Kleffner syndrome." (PMID 38366112, 2024). "Numerous inherited or de novo variants in the GRIN2A gene, encoding the GluN2A subunit of the receptor, have been identified in patients with epilepsy." (PMID 39474911, 2024). "Whole exome sequencing was conducted in enrolled patients with epilepsy‐aphasia syndromes, and GRIN2A variants were screened." (PMID 39474911, 2024). "Functional analyses of disease-associated variants of GRIN2A linked to conditions such as epilepsy or DD/ID have demonstrated both gain- and loss-of-function consequences." (PMID 38307912, 2024). "For instance, iPSCs were generated from peripheral blood mononuclear cells (PBMCs) from a seven-year-old child with epilepsy, who carried a heterozygous mutation of GRIN2A gene (c.1832 A>T)." (PMID 39596430, 2024). "Mutations in GRIN2A are also associated with epilepsy and developmental delay/intellectual disability (DD/ID)." (PMID 38307912, 2024). "GRIN2A is associated with epilepsy (EP); however, its regulatory mechanism involving upstream miRNA (miR-30b-5p) has been overlooked." (PMID 37016703, 2023). "Any mutations in GRIN2A gene weaken ion flow through the receptor, resulting in abnormal neuron function, epilepsy, and related developmental differences." (PMID 37319252, 2023). "AKAP11 and GRIN2A mutations are also associated with bipolar disorder, and epilepsy and developmental delay/intellectual disability, respectively." (PMID 36914641, 2023). "In this study, we have evaluated and compared the phenotypes and mechanisms of synaptic dysfunction in CA1 neurons expressing epilepsy-associated gain- and loss-of-function GRIN2A mutants." (PMID 35228668, 2022). "Dominant mutations in the human gene GRIN2A, encoding NMDA receptor (NMDAR) subunit GluN2A, make a significant and growing contribution to the catalogue of published single-gene epilepsies." (PMID 35228668, 2022).
epilepsy (continued). "A common outcome of these studies is that epilepsy-associated GRIN2A mutations have strikingly variable functional consequences on NMDARs51,52,57,59." (PMID 35228668, 2022). "About 70% of GRIN2A variants are likely to lead to the development of epilepsy, whereas 30% of individuals with GRIN2B variants have epilepsy." (PMID 36297409, 2022). "This included genes like KMT2C, involved in Kleefstra syndrome (OMIM #617768), and GRIN2A of which heterozygous mutations cause epilepsy and speech delay (OMIM #245570)." (PMID 34663447, 2021). "The efficacy of memantine in epilepsy and cognitive improvement with GRIN2A mutations does a good job of explaining why the blockade of NMDA receptors is beneficial for AD." (PMID 34281185, 2021). "Intriguingly, GRIN mutations make up a high proportion of these disease-linked mutations, and GRIN2A mutations, specifically, have been identified as key drivers of epilepsy aphasia spectrum disorders." (PMID 34776984, 2021). "In order to understand the mechanism underlying phenotypic variations, all reported epilepsy-related GRIN2A missense mutations and their functional alterations were reviewed." (PMID 34720871, 2021). "The dysfunction of the GRIN2A gene has been previously implicated in the impairment of learning and memory, intellectual disability, epilepsy and autism, as well as in SCZ and other neurodevelopmental defects." (PMID 34946848, 2021). "Previously, 10 GRIN2A mutations with epilepsy were identified as GOF through two-electrode voltage clamp recordings." (PMID 34720871, 2021). "It is, therefore, possible that GRIN2A mutations will cause neurodevelopmental abnormalities and subsequently secondary epilepsy, for which the underlying mechanism warrants further studies." (PMID 34720871, 2021). "Patients with GRIN2A mutations began to develop neurological abnormalities 1 year after birth and were often accompanied with epilepsy." (PMID 34485298, 2021). "Mutations and polymorphisms in the GRIN2A gene, coding for GluN2A, are linked to developmental brain disorders such as mental retardation, epilepsy, and mental disorders." (PMID 34685369, 2021). "Considering that NMDARs generally mediate excitatory neurotransmission and are critical for the regulation of neuronal excitability in the brain, it potentially explains the association between GRIN2A variants and epilepsy." (PMID 34720871, 2021). "Previously, a de novo mutation in GRIN2A, encoding the GluN2A subunit, was identified in a patient with severe epilepsy and developmental delay." (PMID 34776984, 2021). "More than 60 different mutations of GRIN2A have been found in patients presenting with epilepsy-aphasia spectrum disorders, intellectual disability, and Parkinson’s disease." (PMID 31652432, 2020). "In the example, only SCN1A, DEPDC5 and GRIN2A are in the top 10 ‘epilepsy’ gene list both as genes with the most variants and most pathogenic variants." (PMID 31114901, 2019). "Among all currently known GRIN-associated phenotypes, GRIN2A-related disorders display the most recognizable epilepsy spectrum, comprising focal or multifocal epilepsy with or without centrotemporal spikes as well as CSWS." (PMID 30544257, 2019). "Among 3038 individuals with neurodevelopmental disorders with epilepsy screened by epilepsy panel sequencing (covering GRIN2A) in the same diagnostic lab, seven displayed (likely) pathogenic variants revealing a prevalence of 0.23% in this disease spectrum." (PMID 30544257, 2019). "Grin2a mutations were identified in children with specific language impairment, speech disorders and epilepsy." (PMID 31652960, 2019). "Recognizable epilepsy syndromes comprised the known spectrum of GRIN2A-associated epilepsy syndromes, such as benign epilepsy with centrotemporal spikes, atypical childhood epilepsy with centrotemporal spikes and Landau-Kleffner syndrome." (PMID 30544257, 2019).